KLK8 (kallikrein related peptidase 8)
Diseases named in the same sentence as KLK8 in open-access papers (continued):
Sharing a sentence is not in itself a finding about the gene and the disease.
cardiac hypertrophy (5 papers, 2016 to 2024). "Intracardiac adenovirus-mediated and transgenic-mediated increase in KLK8 led to cardiac hypertrophy in vivo." (PMID 39578836, 2024). "It was found that intra-cardiac KLK8 gene delivery led to a significantly increase in the transcripts of cardiac hypertrophy markers including ANP and Myh7." (PMID 26823023, 2016). "Both intra-cardiac adenovirus-mediated and transgenic-mediated KLK8 overexpression led to cardiac hypertrophy in vivo." (PMID 26823023, 2016). "The KLK8 transgenic rats developed significant cardiac hypertrophy at both 6-weeks and 12-weeks of age." (PMID 26823023, 2016). "Four weeks after intra-cardiac injection of Ad-vector and Ad-KLK8, the anterior wall of LV tissue was obtained for measurement of cardiac hypertrophy markers and histological analysis." (PMID 26823023, 2016). "KLK8 regulates cellular signaling through the cleavage and activation of protease-activated receptors (PARs), which contribute to various cellular effects, including cardiac fibrosis and the development of cardiac hypertrophy." (PMID 39578836, 2024). "The expression of KLK8 increased in the left ventricle of cardiac hypertrophy model mice." (PMID 39578836, 2024). "Although its physiologic substrates remain largely unknown, the expression of Klk8 protects against acute ischemia-reperfusion injury and induces cardiac hypertrophy in rats, in response to pressure overload." (PMID 36672863, 2023). "A previous report showed that KLK8 was expressed in the myocardium and induced cardiac hypertrophy." (PMID 34059001, 2021). "In the present study, we found that KLK8 could release bradykinin in cardiomyocytes, meanwhile significantly promote cardiac hypertrophy." (PMID 26823023, 2016). "Since KLK family members have been observed to be involved in cardiac hypertrophy through modulating ECM synthesis and degradation, whether KLK8 plays a role in aging-associated cardiac hypertrophy merits further investigation." (PMID 26823023, 2016). "KLK8 expression was upregulated in left ventricle of cardiac hypertrophy models." (PMID 26823023, 2016). "As KLK8 expression was increased in hypertrophy heart tissues, we then investigated whether in vivo intra-cardiac adenovirus-mediated KLK8 delivery might lead to cardiac hypertrophy." (PMID 26823023, 2016). "The transcripts of cardiac hypertrophy markers including ANP, BNP and Myh7 were also significantly up-regulated in the heart tissues of KLK8 transgenic rats." (PMID 26823023, 2016). "The present study demonstrates that KLK8, a new member of KLK family, is expressed in cardiomycytes and can induce cardiac hypertrophy." (PMID 26823023, 2016). "Nevertheless, the differences in KLK1 and KLK8 expression pattern in cardiac hypertrophy suggest that KLK1 and KLK8 might play different roles in this cardiac disorder." (PMID 26823023, 2016).
Anxiety (4 papers, 2020 to 2025). Intense feelings of nervousness, tension, or panic often arise in response to interpersonal stresses. "Several studies have suggested the critical role of KLK8 in the pathogenesis of anxiety-related behaviors due to different etiologies." (PMID 37076499, 2023).
diabetes (4 papers, 2021 to 2025). "As anticipated, the upregulation of hippocampal KLK8 induced by diabetes was blunted in KLK8-deficient (KLK8-/-) mice." (PMID 40521191, 2025). "The pivotal role of KLK8 in diabetes-associated cardiomyopathy was also highlighted through our results." (PMID 39578836, 2024). "The present study next observed the effect of KLK8 deficiency on diabetes-induced diastolic dysfunction." (PMID 33754057, 2021). "The present study found that KLK8 deficiency significantly attenuated diabetes-induced increases in the plasma levels of TC and FFA." (PMID 33754057, 2021). "Diabetes-induced endothelial injury and cardiac EndMT were significantly alleviated in KLK8-deficient mice." (PMID 33754057, 2021). "The present study reports for the first time that diabetes mellitus-associated EndMT and fibrosis in the myocardium are stimulated in part by upregulation of KLK8." (PMID 33754057, 2021). "In addition, the molecular mechanisms underlying KLK8-mediated EndMT and cardiac fibrosis in the context of diabetes were illustrated." (PMID 33754057, 2021). "The diabetes-induced upregulation of cardiac KLK8 was blunt in KLK8-deficient (KLK8-/-) mice." (PMID 33754057, 2021). "Mice with global deletion of KLK8 were then used to investigate whether KLK8 deficiency affects diabetes-associated cardiac fibrosis." (PMID 33754057, 2021). "This study elucidates a novel mechanism by which KLK8 upregulation contributes to diabetes-induced microglial activation and neuroinflammation in the hippocampus through modulating the hepatocyte growth factor (HGF)/Met signaling pathway." (PMID 40521191, 2025). "It was found that diabetes-related EndMT and myocardial fibrosis were partly stimulated by the up-regulation of kallikrein-related peptidase 8 (KLK8)." (PMID 37065745, 2023). "Collectively, these findings suggest that upregulation of KLK8 contribute to the development of diabetes mellitus-induced EndMT and cardiac fibrosis." (PMID 33754057, 2021). "Global deletion of KLK8 significantly alleviated diabetes mellitus-induced EndMT and cardiac fibrosis, whereas transgenic overexpression of KLK8 led to interstitial/perivascular fibrosis and EndMT in the myocardium." (PMID 33754057, 2021). "Degradation of VE-cadherin and activation of the plakoglobin-dependent pro-EndMT signaling pathway by KLK8 contribute to the development of EndMT and cardiac fibrosis and accelerate the progression to cardiac dysfunction in diabetes mellitus." (PMID 33754057, 2021). "Methods and Results-By screening gene expression profiles of KLKs, it was found that KLK8 was highly induced in the myocardium of mice with streptozotocin-induced diabetes." (PMID 33754057, 2021). "KLK8 activates platelet hemoglobin-dependent pro-EndMT signaling pathway, contributes to the evolution of EndMT and cardiac fibrosis, and accelerates the progress of cardiac dysfunction in diabetes." (PMID 37065745, 2023). "Using an STZ-induced diabetes model, a significant increase in the TGF-β1 mRNA and protein levels, as well as in the mRNA levels of TGF-β1 pro-EndMT transcriptional targets, was observed in heart tissues after 24 weeks of diabetes mellitus, which was significantly attenuated in KLK8-/- mice." (PMID 33754057, 2021). "Of note, since KLK8 promotes proliferation and migration in cardiac fibroblasts, a potential contribution of KLK8-induced fibroblast activation to the development of cardiac fibrosis in the context of diabetes cannot be excluded." (PMID 33754057, 2021). "However, 24 weeks of diabetes mellitus led to significant increases in systolic, diastolic and mean arterial blood pressure in KLK8+/+ mice, which were significantly attenuated in KLK8-/- mice." (PMID 33754057, 2021).
diabetes (continued). "It was found that KLK8 deficiency partially rescued the reduced E/A ratio, and reduced E-wave deceleration time and IVRT in STZ-induced diabetic mice, suggesting that KLK8 deficiency prevented further deterioration of diastolic function during diabetes progression." (PMID 33754057, 2021). "In the animal model, diabetes mellitus led to an increase in the plasma levels of thrombomodulin, VWF and E-selectin in KLK8+/+ mice, which were significantly attenuated in KLK8-/- mice." (PMID 33754057, 2021). "The absence of KLK8 effectively ameliorated diabetes-induced cardiac fibrosis." (PMID 39578836, 2024).
melanoma (4 papers, 2011 to 2025). A malignant, usually aggressive tumor composed of atypical, neoplastic melanocytes. "Analysis of the influence of Activin-A processing on SMAD3 signaling in a reporter cell line after Klk8 knockdown in furin-deficient B16-F1 melanoma cells revealed that this kallikrein converts proActivin-A to A70 independently of furin." (PMID 40064965, 2025). "To selectively block the direct effect of Klk8 on Activin-A, we analyzed B16-F1 melanoma grafts that secrete the KLK8-resistant proActivin-A encoded by R310A mutant βA." (PMID 40064965, 2025). "Interestingly, Kaplan-Meier plots revealed that high KLK8 expression is associated with shorter overall patient survival both in melanoma, and in 9 out of 12 other cancer types analyzed." (PMID 40064965, 2025). "Taken together, these results strongly support a role for Klk8 in promoting melanoma growth by contributing to Activin-A precursor processing, even though this contribution can be obscured by the overlapping activity of furin." (PMID 40064965, 2025). "Recent studies also identified KLK8 among useful markers to predict cancer progression and immune response and to classify melanoma into subgroups to select distinct treatments." (PMID 40064965, 2025). "To directly validate knockdown efficiency, we transfected Klk8 siRNAs into YUMM3.3 mouse melanoma cells since Klk8 mRNA levels in B16-F1 cells were too low for reliable quantification." (PMID 40064965, 2025). "Here, an RNAi screen for proteases mediating A70 formation in Furin knockout B16-F1 melanoma cells identified Klk8." (PMID 40064965, 2025). "Human KLK8 expression correlated with poor patient outcomes in many cancer types, including melanoma, suggesting that inhibition of KLK8 holds promise as a future therapeutic strategy." (PMID 40064965, 2025). "Mutating the fifth arginine of this motif to alanine abolished hemicleavage by KLK8 and the tumor growth advantage of syngeneic B16-F1 melanoma grafts conferred by Activin-A." (PMID 40064965, 2025). "KLK8 was also involved in the progression of melanoma, which further suggested the tumor-promoting role of KLK8." (PMID 38273291, 2024). "In melanoma, KLK8, TIGIT, and TRIM63 were identified as the representative three-gene classifier for melanoma molecular subtypes to predict patients’ survival risk." (PMID 38273291, 2024). "Melanoma patients with low KLK8 and high TIGIT were classified as the “Immune” subtype, a molecular subtype with favorable survival." (PMID 38273291, 2024). "All lymph node specimens stained negatively for the KLK8 gene, the predictor for the primary melanoma enriched “Keratin” subgroup in the tree (first row), indicating that the six samples do not belong to that subgroup." (PMID 33564068, 2021). "In melanoma, KLK8 expression peaked during the transition of primary tumor to metastatic disease." (PMID 40064965, 2025). "Importantly, the growth of B16-F1 melanoma secreting Activin-A also decreased upon depletion of Klk8, despite the overlapping activity of furin." (PMID 40064965, 2025). "We also analyzed KLK8 expression in a panel of 13 human melanoma cell lines." (PMID 40064965, 2025). "Moreover, knockdown of Klk8 in syngeneic melanoma grafts suppresses Activin-A induced tumor growth, demonstrating that cleavage by only furin is not sufficient." (PMID 40064965, 2025). "Besides revealing significant KLK8 expression in skin and in multiple cancer types, including melanoma, these results indicate that a potential role for Activin-A signaling in promoting KLK8 expression is unlikely a common feature among skin melanoma at all tumor stages." (PMID 40064965, 2025). "However, a majority of human and murine melanoma cell lines analyzed here expressed KLK8 mRNA." (PMID 40064965, 2025). "To evaluate a possible interaction of KLK8 with Activin-A in vivo, we assessed its correlation with INHBA expression in human melanoma." (PMID 40064965, 2025).
melanoma (continued). "The produced decision tree consists of three informative genes (KLK8, TIGIT, and TRIM63) along with a threshold level for each gene, which together provide a simple method for classifying melanoma tumors into one of the four subgroups." (PMID 33564068, 2021). "Some of these genes had already been described in earlier studies as being down-regulated during melanoma progression: COL17A1, DSC3, KLK7, SLPI and KLK8, or over-expressed, e.g. CCL20, THBS1 and THBS4." (PMID 22032772, 2011). "The present study confirms these associations at the transcriptional level and shows that not only KLK6 and KLK7 but other hKLKs such as KLK8 and KLK13 are probably coordinately involved in melanoma progression." (PMID 22032772, 2011). "We found that IPTG-inducible Klk8 shRNAs specifically impaired the growth of B16F1-βA melanoma grafts, but not of B16F1-Ctrl tumors." (PMID 40064965, 2025). "To directly test if Klk8 and furin activities complement each other in vivo, we expressed the IPTG-inducible control shLuc or Klk8 shRNAs in B16F1 FurKO-βA melanoma grafts lacking furin." (PMID 40064965, 2025). "By contrast, total activity in reporter cells without CMK was not significantly depleted, even though Klk8 RNAi tended to also diminish the levels of proActivin-A and its signaling activity, correlating with a decrease in viable melanoma cells." (PMID 40064965, 2025). "Regardless of the mechanism, our findings identify KLK8 as an attractive strategy to block the stimulation of tumor growth by Activin-A, at least in melanoma." (PMID 40064965, 2025). "For melanoma progression category (T3, T4 and MM), only genes ontologically-related to hKLKs (EVPL, KLK6, KLK7, KLK8, KLK13 and SERPINB13) showed a positive and high correlation coefficient (mean of 0.971) in T4 thick melanomas (depth > 4.0 mm), but not in metastatic tumors (MM)." (PMID 22032772, 2011). "Furthermore, at different stages of melanoma progression, tumors expressing KLK8 were more frequent among patients at stage II, whereas no such enrichment was observed at more advanced stages." (PMID 40064965, 2025). "This study was the first to report a coordinated decrease in mRNA expression levels of hKLKs (KLK6, KLK7, KLK8 and KLK13) as melanoma cells emerges from primary to metastatic phenotype, suggesting a role of these proteases in the epithelial-mesenchymal transition of primary melanoma cells." (PMID 22032772, 2011). "In at least two of these, KLK8 expression increased in the presence of Activin-A, even though KLK8 and INHBA were not consistently co-expressed in the human melanoma cohort examined here." (PMID 40064965, 2025).
schizophrenia (4 papers, 2020 to 2023). A major psychotic disorder characterized by abnormalities in the perception or expression of reality. "The 19q13 genomic region, in which KLK8 is located, has been implicated in both schizophrenia and bipolar disorder by genetic linkage studies, and genetic common variation in KLK8 has been associated with bipolar disorder and cognitive functioning." (PMID 34715912, 2021).
bipolar disorder (3 papers, 2019 to 2021). A disorder of the brain that causes unusual shifts in mood, energy, activity levels and the ability to carry out day-to-day tasks. "KLK8, also known as neuropsin, encodes a serine protease and maps to chromosome 19q13, a region implicated in schizophrenia and bipolar disorder by genetic linkage studies." (PMID 31477683, 2019).
fibrosis (3 papers, 2016 to 2024). the formation of excess fibrous connective tissue in an organ or tissue in a reparative or reactive process. "Masson’s staining showed that the extent of cardiac fibrosis was comparable in LV tissues obtained from 6-weeks-old KLK8 transgenic rats or 6-weeks-old control rats." (PMID 26823023, 2016). "Masson’s staining showed that the extent of cardiac fibrosis was comparable in LV tissues obtained from rats injected with Ad-KLK8 or control adenovirus." (PMID 26823023, 2016).
lung adenocarcinoma (3 papers, 2018 to 2024). A carcinoma that arises from the lung and is characterized by the presence of malignant glandular epithelial cells. "Increased KLK8 has been associated with a favorable clinical outcome in lung adenocarcinoma by suppressing tumor invasiveness through inhibition of integrin signaling and cell adhesion; however we could not confirm this finding in our study." (PMID 29707153, 2018). "Univariate Cox regression analysis suggested that the high expression levels of up-regulated DEGs including APOL1, ETFB, KLK8, PPP1R3G, PRL, and SPTA1 were significantly correlated with poorer overall survival (OS) in lung adenocarcinoma." (PMID 38183079, 2024). "Lung adenocarcinoma and lung squamous cell carcinoma showed significant up-regulation of 3 KLKs: KLK6 (7-fold and 19-fold), KLK8 (3-fold and 15-fold) and KLK12 (2-fold and 3-fold) and significant down-regulation of KLK11 (6-fold and 5-fold)." (PMID 29707153, 2018).
clear cell renal cell carcinoma (2 papers, 2018 to 2025). "Renal clear cell carcinoma had six KLKs in which increased expression was associated with overall survival (KLK2: HR = 1.69; KLK4: HR = 1.63; KLK8: HR = 1.71; KLK10: HR = 2.12; KLK11: HR = 1.76; and KLK14: HR = 1.86)." (PMID 29707153, 2018).
esophageal cancer (2 papers, 2024). A primary or metastatic malignant neoplasm involving the esophagus. "The positively correlated genes (SLUT2B1, PPL, KLK6, CRYBG2, SCEL, ADGRF4 and KLK8) were more frequently expressed in esophageal cancer than normal tissue (p < .05)." (PMID 38241178, 2024).
head and neck squamous cell carcinoma (2 papers, 2014 to 2015). A squamous cell carcinoma that arises from any of the following anatomic sites: lip and oral cavity, nasal cavity, paranasal sinuses, pharynx, larynx, and salivary glands. "Correlative studies have already provided evidence that five other protein members of KLK family (KLK4, KLK5, KLK7, KLK8, and KLK10) were abundantly expressed in head and neck squamous cell carcinoma, showing diagnostic value." (PMID 24669031, 2014).
Hyperglycemia (2 papers, 2021 to 2025). An increased concentration of glucose in the blood. "Furthermore, we elucidated the molecular mechanisms underlying KLK8-mediated microglial activation in the context of hyperglycemia." (PMID 40521191, 2025). "In the present study, we demonstrated for the first time that hyperglycemia-induced KLK8 upregulation per se was sufficient to induce microglial activation and neuroinflammation." (PMID 40521191, 2025). "We documented for the first time that hyperglycemia-induced upregulation of KLK8 was a critical event capable of initiating microglial activation and neuroinflammation." (PMID 40521191, 2025). "STZ-induced low insulin levels and hyperglycemia occurred in both KLK8-/- and KLK8+/+ mice, whereas the levels of insulin and blood glucose in non-diabetic mice were normal." (PMID 33754057, 2021).
Myocardial fibrosis (2 papers, 2023 to 2024). "We also assessed whether GAS attenuates myocardial fibrosis through the KLK8/PAR1 signaling axis." (PMID 39578836, 2024). "Additionally, the results of molecular docking analysis showed that GAS binds to kinin-releasing enzyme-related peptidase 8 (KLK8) to inhibit the increase in protease-activated receptor-1 (PAR-1), thus attenuating myocardial fibrosis." (PMID 39578836, 2024).
prostate carcinoma (2 papers, 2018 to 2020). A carcinoma that arises from epithelial cells of the prostate gland. "Patients with recurrent prostate cancer might have a loss of KLK8 gene sequences or are affected by other factors." (PMID 33150763, 2020). "Although in our study KLK8 was upregulated in both recurrent and non-recurrent prostate cancer tissues, its expression was lower in recurrent than in non-recurrent cancer." (PMID 33150763, 2020). "In conclusion, we propose that KLK1, KLK2, KLK3 KLK4, KLK8, KLK9, and KLK14, which are differentially expressed in prostate cancer, could be used as promising biomarkers of prostate cancer progression." (PMID 33150763, 2020). "Our results point to the fact that KLK1, KLK2, and KLK14 (only in recurrent prostate cancer tissues) are underexpressed in prostate cancer tissues, while KLK3, KLK4, KLK8, and KLK9 are overexpressed in both recurrent and non-recurrent tissues." (PMID 33150763, 2020).